TIMP1 (TIMP metallopeptidase inhibitor 1)
Diseases named in the same sentence as TIMP1 in open-access papers (continued):
Sharing a sentence is not in itself a finding about the gene and the disease.
Sepsis (continued). "Simultaneously, the platelet-secreted factors TSP, PF4, TIMP-1 and TCK-1 changed significantly during the first 6 h post-CLP and were therefore regarded as meaningful biomarkers of the early stage of sepsis-induced DIC." (PMID 23497204, 2013). "Sepsis patients had higher levels of MMP-10 and TIMP-1, higher MMP-10/TIMP-1 ratios, and lower MMP-9/TIMP-1 ratios than did healthy controls (P < 0.001)." (PMID 19799791, 2009). "Serum levels of MMP-9, MMP-10, TIMP-1, tumor necrosis factor (TNF)-alpha, and interleukin (IL)-10 were measured in patients with severe sepsis at the time of diagnosis and in healthy controls." (PMID 19799791, 2009). "The levels of TIMP1, PF4, and CXCL7 proteins varied across sepsis subgroups in this study." (PMID 40864331, 2025). "Earlier studies have shown that plasma MMP-9 concentrations may be a useful prognostic marker in septic shock, TIMP-1/MMP-9 ratio is correlated with sepsis severity and coagulation index, and may be a new biomarker of sepsis outcome." (PMID 38029239, 2023). "The prognostic role of TIMP1 and MMP9 during sepsis was confirmed by another study." (PMID 37817235, 2023). "TIMP-1 concentrations in the group negative for sepsis were 472.4 (289.4–765.1) ng/ml in plasma and 223.7 (180.4–272.9) ng/ml in PF, respectively." (PMID 33488296, 2021). "Previous reports have presented admission TIMP-1 as an independent negative prognostic marker for 30–90 days or overall mortality in critically ill, severe sepsis or acute respiratory failure patients." (PMID 34043679, 2021). "MMP-8 and MMP-8/TIMP-1 ratio were high 3–5 days after MS-SAB diagnosis in patients with an infection focus, severe sepsis or mortality within 14 days suggesting that matrix metalloproteinase activation might play a role in severe SAB." (PMID 34043679, 2021). "Interestingly, in severe sepsis, the expression levels of MMP-9, TIMP-1, and TIMP-2 are also significantly elevated." (PMID 31671729, 2019). "AUC-ROC for diagnosis of sepsis was 0.940 and 0.854 for TIMP-1 and 0.924 and 0.788 for MMP-9/TIMP-1 ratio (sepsis versus nonoperated and sepsis versus operated controls, resp)." (PMID 29861795, 2018). "In addition, NGAL, MMP-9, TIMP-1 levels and MEDS score were significantly higher in sepsis, severe sepsis and septic shock than in SIRS (P <0.01)." (PMID 25407832, 2014). "Our study suggests that the prognostic value of NGAL, MMP-9 or TIMP-1 is superior to PCT and MEDS score, and that NGAL, TIMP-1, MMP-9 or MEDS score, but not PCT, are robust independent predictors of 28-day death in patients with sepsis." (PMID 25407832, 2014). "Higher circulating levels of tissue inhibitor of matrix metalloproteinases (TIMP)-1 at the time of severe sepsis diagnosis have been reported in nonsurviving than in surviving patients." (PMID 24727739, 2014). "Previous clinical studies including our own have shown higher circulating levels of MMP-9 and TIMP-1 in septic patients than in controls, and higher levels of TIMP-1 at the time of severe sepsis diagnosis in non-surviving than in surviving patients." (PMID 24727739, 2014). "NGAL, TIMP-1, PCT levels and MEDS score were markedly higher in severe sepsis and septic shock than in sepsis (P <0.01), and were clearly higher in septic shock than in severe sepsis (P <0.01)." (PMID 25407832, 2014). "TSP, TIMP-1 and TCK-1 are elevated in the early stage of sepsis-induced DIC in a mouse CLP model and may be considered early markers for sepsis-induced DIC." (PMID 23497204, 2013). "Hoffmann and colleagues, demonstrated elevated plasma levels of MMP-9 and tissue inhibitors of matrix metalloproteinases (TIMP)-2, and TIMP-1 on the first day of severe sepsis and significantly higher TIMP-1 levels in non-surviving patients." (PMID 20356362, 2010). "Taken together, these results indicate that an alteration in the MMP-9/TIMP-1 ratio and MMP-10 levels may be of great pathophysiologic significance in sepsis patients." (PMID 19799791, 2009).
Sepsis (continued). "Small clinical studies (with fewer than 40 patients) have shown higher plasma levels of MMP-9 and TIMP-1 in sepsis patients as compared with those observed in controls, and higher levels of TIMP-1 or MMP-9 in nonsurviving than in surviving patients." (PMID 19799791, 2009). "Inflammatory status was assessed in sepsis patients by measuring TNF-α and IL-10, to elucidate whether it could account for differences observed in MMPs and TIMP-1." (PMID 19799791, 2009). "• MMP-9/TIMP-1 ratio and MMP-10 levels may be of great pathophysiologic significance in terms of severity and mortality in sepsis patients." (PMID 19799791, 2009). "Although higher levels of MMP-9 and tissue inhibitor of matrix metalloproteinases-1 (TIMP-1) have been found in small series of patients with sepsis, MMP-10 levels have not been studied in this setting." (PMID 19799791, 2009). "When comparing sepsis subgroups based on their outcomes, five key protein markers—β-actin (ACTB), C-X-C motif chemokine 7 (CXCL7), platelet factor 4 (PF4), fibronectin (FINC), and Metalloproteinase Inhibitor 1 (TIMP1)—were identified as significant discriminators." (PMID 40864331, 2025). "High Pitt bacteremia score, severe sepsis and ICU treatment were associated to higher MMP-8 concentrations at day 3 and day 5 (p<0.01) and higher TIMP-1 at day 3 (p<0.05) whereas no connection to day TIMP-1 was observed." (PMID 34043679, 2021). "As opposed to MMP-9, TIMP-1 levels are repeatedly reported to be higher in sepsis." (PMID 29861795, 2018). "However, the MMP-9 and MMP-9/TIMP-1 ratio was not significantly higher in severe sepsis and septic shock than in sepsis, or in septic shock than in severe sepsis." (PMID 25407832, 2014). "Notably, within the PPI network analysis, key proteins including ICAM1, Resistin, TIMP1, VWF, CRP, and HMGB1 were identified at the central nodes of the network module, revealing a significant difference (P < 0.05) between the normal group and the sepsis group." (PMID 38951753, 2024). "TIMP-1 (p=0.083) and renin (p=0.12) showed a non-significant decrease in response to combined (GENT and PTX) treatment compared to untreated sepsis." (PMID 39963236, 2024). "Previous reports have observed higher MMP-8 on and TIMP-1 at sepsis onset or ICU admission in non-surviving sepsis patients compared to surviving ones." (PMID 34043679, 2021). "Lorente and coworkers found a significant increase of TIMP-1, and nonsignificantly higher MMP-9 levels, in sepsis patients, and both proteins were significantly higher in nonsurvivors." (PMID 32258173, 2020). "TIMP-1 and MMP-9/TIMP ratio were, unlike MMP-9, very good discriminators between patients with sepsis and both control groups at all time points." (PMID 29861795, 2018). "Nonsurviving sepsis patients had lower levels of MMP-9 (P = 0.037), higher levels of TIMP-1 (P < 0.001), lower MMP-9/TIMP-1 ratio (P = 0.003), higher levels of IL-10 (P < 0.001), and lower TNF-α/IL-10 ratio than did surviving patients." (PMID 19799791, 2009). "In our larger study, we found significantly higher levels of TIMP-1, reduced MMP-9/TIMP-1 ratios, and nonsignificantly higher MMP-9 levels in sepsis patients than in healthy controls." (PMID 19799791, 2009). "After analyzing MMPs and TIMP-1 levels in relation to mortality, in our study, we found higher plasma levels of TIMP-1 and lower levels of MMP-9 in nonsurviving sepsis patients." (PMID 19799791, 2009). "Moreover, higher levels of TIMP-1 (P < 0.001), reduced MMP-9 (P = 0.037), and a nonsignificant increase of MMP-10 were found in nonsurviving as compared with surviving sepsis patients." (PMID 19799791, 2009).
pancreatic cancer (49 papers, 1996 to 2026). "Studies suggest that TIMP1 levels have been linked to the prognosis of several cancer types, including breast and pancreatic cancer." (PMID 41465391, 2025). "Increased levels of TIMP-1 are also associated with cachexia in patients with chronic pancreatitis and pancreatic cancer." (PMID 38201509, 2023). "Since chronic pancreatitis has been identified as a risk factor for PDAC, TIMP-1 warrants further attention as a potential biomarker to stratify patients with chronic pancreatitis based on their risk of pancreatic cancer." (PMID 29903049, 2018). "Also, in accordance with our data, plasma extracellular vesicle long RNA profiling has identified a diagnostic signature, which includes the TIMP1 transcript, for the detection of pancreatic cancer." (PMID 32197468, 2020). "Upregulation of TIMP-1 expression has also been identified as a potential resistance mechanism of pancreatic tumors against gemcitabine, and has been implicated in clonogenic survival of pancreatic cancer cells as well as vascular density." (PMID 29903049, 2018). "In addition, due to the difficulty in diagnosing pancreatic cancer, studies have demonstrated that TIMP1 may serve as an early diagnostic marker for pancreatic cancer." (PMID 32420905, 2020). "Several studies have shown that TIMP1 can promote the invasion and metastasis of pancreatic cancer cells to the liver and perineural areas." (PMID 40687427, 2025). "For example, TIMP1 secreted by pancreatic cancer cells stimulates Schwann cells and promotes peripheral nerve invasion, while TIMP1 knockdown suppresses this invasive behavior." (PMID 40149585, 2025). "Among them, pancreatic cancer cells in the cluster 8 with TIMP1+/FN1+ showed the strongest resistance, while the cluster 1 with CLDN18-/CEACAM5- and the cluster 7 with HSPA6+/NEAT1+ showed milder resistance." (PMID 38343537, 2024). "Other preclinical data also show that suppressing the interaction of TIMP-1 with the CD63 receptor on hepatic stellate cells effectively prevented liver PMN formation in pancreatic cancer models." (PMID 37350937, 2023). "Although gemcitabine-induced TIMP1 secretion attenuates the therapeutic response and promotes tumor growth and liver metastasis in pancreatic cancer, the detailed mechanism of TIMP1 secretion regulated by secretory autophagy remains elusive." (PMID 36457117, 2022). "TIMP1 activated hepatic stellate cells via CD63 signaling to create a premetastatic niche in pancreatic cancer." (PMID 35281807, 2022). "Down-regulation of TIMP1 was found to enhance gemcitabine sensitivity and reverse chemoresistance in pancreatic cancer." (PMID 35281807, 2022). "Zhang and co-workers demonstrated that CD82 mediated the suppressive effect of TIMP-1 on the migratory activity of the pancreatic cancer PANC-1 cells." (PMID 36291767, 2022). "Circulating levels of TIMP-1 are upregulated in different cancer types such as gastric, lung, breast, colorectal, and pancreatic cancer." (PMID 33925872, 2021). "There is a large body of evidence showing that systemic TIMP-1 levels have prognostic value in pancreatic cancer." (PMID 29394913, 2018). "TIMP-1 expression positively correlates with the degree of desmoplasia in the tumor stroma, as well as with de-differentiation of pancreatic tumor cells." (PMID 29394913, 2018). "Previous studies found that TIMP-1–expressing pancreatic cancer cells were significantly less invasive, and mice receiving TIMP-1 adenovirus showed reduced cancer cell growth and prolonged survival rates." (PMID 28030805, 2017). "Three of the 5 candidate proteins, including GSN, lumican (LUM; a member of the SLRP family), and TIMP1, demonstrated an AUC value above 0.75 in differentiating pancreatic cancer from the controls." (PMID 24708694, 2014). "TIMP1 has been previously shown to reduce pancreatic cancer cell growth, metastasis, and angiogenesis, while increasing tumor apoptosis." (PMID 24708694, 2014).
pancreatic cancer (continued). "They found that metallopeptidase inhibitor 1 (TIMP1), a natural tissue inhibitor of matrix metalloproteinases (MMPs) which degrade extracellular matrix, was identified as a biomarker candidate for pancreatic cancer." (PMID 24708694, 2014). "Most recently, the combination of OPN, TIMP-1 and CA 19-9 was found to be effective in the discrimination of patients with pancreatic cancer from a group of healthy controls and patients diagnosed with pancreatitis." (PMID 24747429, 2014). "Recent findings have generated interest in two potential biomarkers, osteopontin (OPN) and TIMP-1, in the early detection of pancreatic cancer." (PMID 24747429, 2014). "Before the operation, the mean concentration of TIMP-1 was higher in patients with pancreatic tumors than in the control group." (PMID 23768069, 2013). "In the evaluation of tissue inhibitors of metalloproteinases, significantly higher mean concentrations of TIMP-1 were observed before the planned surgery in the groups with benign changes or lower advanced stages of pancreatic cancer." (PMID 23768069, 2013). "In pancreatic cancer, TIMP1 promotes neutrophil extracellular trap formation, driving tumor progression, yet its absence may impair immune defenses." (PMID 40687427, 2025). "Studies have shown that TIMP1 can be used as a soluble marker for pancreatic cancer." (PMID 40432920, 2025). "TIMP-1 is also known to elicit NETosis, particularly in the context of pancreatic cancer." (PMID 35200382, 2022). "For example, it has been recently reported that TIMP-1 triggered neutrophil extracellular traps (NETs) formation in patients with pancreatic cancer and there was a significant correlation between TIMP-1 and DNA-bound myeloperoxidase, a NET marker in the plasma." (PMID 36482481, 2022). "In a study investigating the association of plasma TIMP-1 level with cachexia in pancreatic cancer patients, elevated TIMP-1 levels were found in patients with weight loss and without jaundice." (PMID 33925872, 2021). "Pancreatic cancer TIMP1 stimulates neutrophils to release NETs via activating CD63-ERK pathway." (PMID 34868992, 2021). "Straightforward inhibition of TIMP-1 might in fact advance the spread of pancreatic cancer cells as a consequence of reduced protease inhibition." (PMID 29903049, 2018). "So far, there is no consensus whether PDAC patients with concomitant jaundice have to be excluded from use of TIMP-1 as a prognostic marker for pancreatic cancer patients." (PMID 29394913, 2018). "TIMP-1-induced production of SDF-1 in the liver could potentially represent one mechanism directing the organotropic metastasis of pancreatic cancer cells, which also express high levels of CXCR4." (PMID 29903049, 2018). "However, in another study, TIMP-1 was indeed associated with pancreatic cancer, but not with a significant weight loss." (PMID 38201509, 2023). "However, in another study using an aptamer-based discovery platform to identify serum protein biomarkers for pancreatic cancer cachexia, TIMP-1 was only associated with stages of cancer but not weight loss." (PMID 33925872, 2021). "The analysis lead to the identification of TIMP-1, FN-1, SPARC, IGFBP-3, LGALS3BP, and GREM1 as the most upregulated glycoproteins in early-stage pancreatic tumor tissues as compared to controls." (PMID 40345589, 2025). "In pancreatic cancer models, TIMP-1 promotes liver PMN by binding to CD63 on hepatic stellate cells, inducing a positive feedback loop that leads to increased TIMP-1 expression and enhanced neutrophil recruitment to the PMN via CXCL12." (PMID 41463352, 2025). "In brain metastases, astrocyte-derived TIMP1 suppresses CD8+ T cell activity, while in pancreatic cancer, TIMP1-CD63-ERK signaling drives neutrophil extracellular trap formation and tumor progression." (PMID 40145096, 2025).
pancreatic cancer (continued). "MMP1, MMP2 and MMP9, as well as their inhibitors, TIMP1 and TIMP2, were detected in pancreatic cancers, and their concentrations correlated with tumor grade, tumor size, invasive characteristics, and metastasis." (PMID 23744510, 2013). "Confirmed genes included genes already reported in the literature and proposed as biomarkers of pancreatic cancer such as S100A6, TIMP1, NF-κB, VCL and S100P." (PMID 22078386, 2011). "This set included genes already reported in the literature as differentially expressed in pancreatic cancer and that have been investigated as biomarkers for pancreatic cancer (i.e. S100A6, S100P, TIMP1 and NF-κB)." (PMID 22078386, 2011). "Unlike its role as a pro-tumorigenic factor in CRC, TIMP1 exhibits dual functionality in pancreatic cancer." (PMID 40687427, 2025). "TIMP-1 was also included in a three-biomarker panel along with CA 19-9 and carcinoembryonic antigen (CEA), which provided a SN/SP of 76/90 for the classification of pancreatic cancer from benign pancreatic disease." (PMID 24747429, 2014). "The role of TIMP-1 in pancreatic cancer has not received much attention to date." (PMID 28030805, 2017). "One investigation demonstrates no significant change in TIMP-1 and TIMP-2 in Panc-1, pancreatic cancer cells after gamma irradiation." (PMID 27659937, 2016).